AQP4 (aquaporin 4)
Diseases named in the same sentence as AQP4 in open-access papers (continued):
Sharing a sentence is not in itself a finding about the gene and the disease.
schizophrenia (10 papers, 2017 to 2025). A major psychotic disorder characterized by abnormalities in the perception or expression of reality. "Studies on genetic associations have linked the AQP4 gene to schizophrenia in Southern Han Chinese populations, with risk variants correlating with the severity of negative symptoms and inadequate neuroinflammatory regulation." (PMID 39940642, 2025). "The present study is focused on the association between AQP4 gene polymorphisms and schizophrenia (SCZ) in the Southern Chinese Han population." (PMID 32676041, 2020). "On the contrary, AQP4 overexpression that lacks correct perivascular polarization reduces solute clearance and aggravates schizophrenia-like behaviors in rodents." (PMID 40896232, 2025). "A significant reduction in AQP4 expression in the deep layers of the anterior cingulate cortex in schizophrenia patients has been confirmed." (PMID 39940642, 2025). "Previous research has emphasized the crucial role of AQP4 in various brain pathologies, including schizophrenia." (PMID 39940642, 2025). "In schizophrenia model mice, the polarized distribution of AQP4 in the brain is disrupted, and the expression level of AQP4 protein in the model group is significantly reduced compared to the control group." (PMID 39940642, 2025). "AQP4 expression has been documented to be significantly reduced in the deep layers of the anterior cingulate gyrus in schizophrenia subjects." (PMID 28588507, 2017). "Case-control genetic studies show that polymorphisms in AQP4, the main astrocytic water channel involved in glymphatic flux, are linked with an increased risk of schizophrenia, higher serum S100B levels, and more severe negative symptoms." (PMID 40896232, 2025). "In addition, recent findings have demonstrated increased AQP4 expression in the prefrontal cortex and hippocampus of MK-801-induced schizophrenia mouse models." (PMID 39940642, 2025). "Genetic and translational research indicates that AQP4 dysregulation plays a role in schizophrenia." (PMID 40896232, 2025). "In conclusion, a systematic exploration has been conducted on the intricate role of blood–brain barrier (BBB) dysfunction in schizophrenia, effectively bridging the divide between molecular biomarkers such as aquaporin-4 (AQP4) and advanced neuroimaging techniques like arterial spin labeling (ASL)." (PMID 39940642, 2025). "The involvement of AQP4 in the pathophysiology of schizophrenia remains insufficiently understood." (PMID 39940642, 2025). "Furthermore, bioinformatics analyses have identified AQP4 as a critical gene involved in schizophrenia." (PMID 39940642, 2025). "Notably, certain AQP4 single nucleotide polymorphisms (e.g., rs1058424, rs335929, rs3763043) are associated with more severe negative symptoms in schizophrenia and the need for higher doses of olanzapine for symptom control." (PMID 40427508, 2025). "Thus, reduced AQP4 expression in schizophrenia individuals may contribute to neurovascular dysfunction and BBB hyperpermeability." (PMID 28588507, 2017). "The present discussion highlights the critical role of blood–brain barrier (BBB) dysfunction in schizophrenia and emphasizes the importance of integrating arterial spin labeling (ASL) and aquaporin–4 (AQP4) research." (PMID 39940642, 2025). "Combining ASL technology with AQP4 research offers a novel approach to understanding and addressing BBB dysfunction in schizophrenia." (PMID 39940642, 2025). "The pathological mechanism by which altered AQP4 expression impacts glial cell function and damages the BBB in schizophrenia patients requires further investigation." (PMID 39940642, 2025). "More studies are needed to investigate the full effects of reduced AQP4 expression on the functions of neurovascular endothelium and BBB in schizophrenia." (PMID 28588507, 2017).
congenital hydrocephalus (9 papers, 2010 to 2025). Hydrocephalus that is present at birth. "Aquaporin-4 (AQP4) expression is associated with the development of congenital hydrocephalus due to its structural role in the ependymal membrane." (PMID 39125902, 2024). "A better understanding of the molecular interactions among AQP4, Spp1, and microglial activity may therefore provide new insights into the pathophysiological mechanisms of congenital hydrocephalus and suggest potential avenues for therapeutic intervention." (PMID 41226330, 2025). "The absence of this compensatory mechanism, for unknown reasons, could occur in a small number of AQP4−/− mice in which congenital hydrocephalus has been reported." (PMID 38956598, 2024). "Recently, an increase in AQP4 has been reported in the CSF in human congenital hydrocephalus, which could be the result of ependyma denudation and subsequent diffusion of AQP4 from the parenchyma to the CSF." (PMID 25165051, 2014). "AQP4 was found to be high compared to the control in the CSF in congenital hydrocephalus patients." (PMID 23659378, 2013). "In an experimental study of congenital hydrocephalus using the H-Tx rat it was suggested that AQP4 could be important for developing alternative CSF-absorption pathways." (PMID 21054845, 2010). "Therefore, the increase of AQP4 in the CSF in congenital hydrocephalus could be due to the fact that AQP4 passes from the parenchyma to the CSF and this AQP4 movement may be a consequence of ependyma denudation." (PMID 23659378, 2013).
diabetic retinopathy (9 papers, 2014 to 2024). "Taken together, it seems that VEGF, ROS, and AQP4 are closely linked in the retina, and that the unbalance between them may contribute to the development of diabetic retinopathy and DME." (PMID 32230876, 2020). "Hyperglycemic conditions induce an increase in AQP4 expression in MC, and AQP4 knockdown in diabetic animals exacerbates diabetic retinopathy." (PMID 36090789, 2022). "Knockdown of AQP-4 in a model of diabetic retinopathy resulted in increased expression of inflammatory molecules, including IL-6 and VEGF." (PMID 36347836, 2022). "In another study, endothelin-2 was found to inhibit NADPH oxidase, and endothelin-2-injected mice with injured blood-retinal barrier observed in diabetic retinopathy showed increased expressions of AQP4 in the retina." (PMID 32230876, 2020). "Inhibition of AQP4 was neuroprotective in retinal ischemia, but it significantly exacerbated diabetic retinopathy and light-induced retinal damage." (PMID 27438827, 2016). "This is because AQP4 inhibition is neuroprotective of retinal ischemia, but it can exacerbate diabetic retinopathy and light-induced retinal damage." (PMID 25479407, 2014). "Therefore, AQP4 has been suggested as a novel therapeutic target for the treatment of diabetic retinopathy, while the redox state is also important." (PMID 32230876, 2020). "Since it has been shown that AQP4 is involved in the generation of diabetic retinal edema through a redistribution of its expression, AQP4 has been suggested as a novel therapeutic target for the treatment of diabetic retinopathy." (PMID 26346093, 2015). "Therefore, regulation of retinal function by AQP4 may attenuate diabetic retinopathy, offering a promising therapeutic strategy for diabetic retinopathy." (PMID 29565290, 2018). "Whereas AQP4 inhibition was neuroprotective in a retinal ischemia model, streptozotocin-induced diabetic retinopathy and light-induced retinal damage worsened without AQP4 expression." (PMID 27438827, 2016).
optic disc edema (9 papers, 2016 to 2025). "On the other hand, atypical features, such as prominent optic disc edema, poor treatment response, and bilateral involvement are often associated with autoantibodies against aquaporin-4 (AQP4) and Myelin Oligodendrocyte Glycoprotein (MOG)." (PMID 37958968, 2023). "The most common papillitis are idiopathic, demyelinating, and antibody-mediated (aquaporin-4 and antimyelin oligodendrocyte glycoprotein (MOG))." (PMID 37987292, 2023). "MOG-ON had a higher rate of optic disk edema than ION and AQP4-ON (83.3 vs. 61.9%, p = 0.019 and 83.3 vs. 25.9%, p = 0.016, respectively)." (PMID 36507533, 2022). "MOG-ON had a higher rate of optic disk edema than the ION and AQP4-ON groups, which corresponded to the results of our previous studies." (PMID 36507533, 2022). "Patients with bilateral papillitis relapsing ON who show steroid dependency in the absence of the AQP4-Ab must be tested for MOG-IgG." (PMID 39692830, 2025). "Moreover, acetazolamide is known to inhibit water conduction by AQP-4 and its use in IIH patients has a direct effect on papilledema and intracranial pressure, and significantly improves visual field function in patients with IIH." (PMID 37724184, 2023).
thyroid (9 papers, 2017 to 2025). "After thyroid function normalizes, astrocyte aquaporin-4 (AQP4) regulation can resolve edema, and rapid oligodendrocyte precursor cell migration can fulfill myelin repair needs." (PMID 41357835, 2025). "AQP4-IgG may cross-react with thyroid antigens, leading to thyroid dysfunction and amplifying systemic autoimmunity." (PMID 40933045, 2025). "In the AQP4-NMOSD cohort, 28% (n = 49) had at least one AID, compared to 11.3% (n = 25) in the MOGAD cohort (p < 0.001), with thyroid disease constituting the majority of these cases in both groups." (PMID 40495001, 2025). "In the present study, we also investigated tumor markers, onconeural antibodies and coexistent anti-thyroid autoantibodies, anti-nuclear/myositis/ganglioside antibody profiles, and anti-MPO/PR3/AchR/AQP4 antibodies." (PMID 29180979, 2017).
hemorrhagic stroke (8 papers, 2015 to 2025). A stroke caused by a bleed on the brain. "For example, AQP4 expression in astrocytic endfeet has been shown to be responsible for the development of the cerebral edema during hemorrhagic stroke." (PMID 32252790, 2020). "HBO-PC also appears to play a neuroprotective role in the progression of hemorrhagic stroke, resulting in the downregulation of AQP4 expression around the hemorrhagic focus and the prevention of edema formation in an ICH rat model." (PMID 27438832, 2016). "The development of suitable therapeutic interventions poses a complex problem due to the bimodal role of AQP4 in edema progression and its opposing actions in ischemic and hemorrhagic stroke." (PMID 27438832, 2016). "Upregulation of AQP4 improved perivascular polarization, reduced iron deposition, and improved neurological outcomes, while TGN-020 inhibition or AQP4 knockout impaired these effects; these findings reinforce the role of AQP4 as a therapeutic target in hemorrhagic stroke." (PMID 40943104, 2025). "The contradictions between the two studies may be related to the difference in SAH models, or it may mean that AQP4 has a biphasic effect after a hemorrhagic stroke." (PMID 34421575, 2021).
lung carcinoma (8 papers, 2021 to 2026). "Although CV2/CRMP5 antibodies are typically linked to lung cancer and thymoma, their coexistence with AQP4-IgG in NMOSD points to a distinct paraneoplastic mechanism." (PMID 41878006, 2026). "Studies suggest that altered AQP4 levels may influence tumor cell migration and are associated with lung cancer prognosis." (PMID 40565055, 2025). "A significant reduction in the migration of AQP1 shRNA and AQP4 shRNA cells was observed compared to control lung cancer cells." (PMID 38681779, 2023). "On the contrary, studies found that AQP4 is highly expressed in lung cancer and is involved in the invasion of lung cancer cells." (PMID 36203529, 2022). "In this study, we first systematically analyzed the expression of eight AT II-associated genes (AQP4, SFTPB, SFTPC, SFTPD, CLDN18, FOXA2, NKX2-1, and PGC) in lung cancer." (PMID 36203529, 2022). "In this study, we comprehensively analyzed the gene expression, prognosis value, genetic alteration, and immune cell infiltration of eight AT II-associated genes (AQP4, SFTPB, SFTPC, SFTPD, CLDN18, FOXA2, NKX2-1, and PGC) in Nonsmall Cell Lung Cancer (NSCLC)." (PMID 36203529, 2022). "Additionally, three MOG-ON patients experienced fatigue preceding their illness, and one patient from the AQP4-ON group was diagnosed with lung cancer a year before developing neurological symptoms." (PMID 38988608, 2024). "By intersecting these top DEGs, we recognized seven genes potentially involved in the pathogenesis of both SSc and lung cancer: SCN7A, AGTR1, WIF1, PRKG2, LTF, AQP4, and COL10A1." (PMID 39744538, 2024). "In terms of individual molecules, most of them were studied in human cancers, including lung cancer (e.g., AQP1, AQP4, IL33, and PEBP4)." (PMID 35211471, 2022).
sleep disorder (8 papers, 2022 to 2026). A change from the patient's baseline sleeping pattern, in the hours slept and/or an alteration/dysfunction in the stages of sleep. "If our hypotheses are going to be confirmed, AQP4 modulation may represent the convergence point between AD and sleep disorder pathogenic mechanisms." (PMID 36653878, 2023). "AQP4 may be a common pathogenic mechanism in neurodegenerative diseases and sleep disorders." (PMID 38338949, 2024). "In conclusion, sleep disorders, such as SD, reduced NREM sleep and OSAHS, can cause synaptic impairment in astrocytes, depolarizing AQP4 and expanding the PVS, ultimately contributing to the deregulation of the glymphatic system and the onset of AD." (PMID 38270115, 2024). "In this article, we shed a new light on the study of AQP4 as one of the possible major markers for the study of sleep disorders in the pathogenesis of AD." (PMID 36653878, 2023). "Melatonin treatment restored the AQP4 polarization and ultimately attenuated the CUMS-induced sleep disorder and associated behavioral outcomes and impairment in spatial memory." (PMID 37802998, 2023). "Clinically, impaired AQP4 polarization may represent a shared pathological feature in populations at high risk for POCD, including elderly individuals, those with chronic inflammation, or sleep disorders." (PMID 40822471, 2025). "Its function relies on several key elements—including optimal sleep architecture, aquaporin-4 (AQP4) polarization, and cerebrovascular dynamics—all of which are commonly impaired in individuals at high risk for POCD, such as older adults or those with sleep disorders and chronic inflammation." (PMID 40822471, 2025). "As the glymphatic fluid movement has been linked to sleep architecture, we investigated cerebrospinal fluid (CSF) Aquaporin-4 (AQP4) as potential biomarker for perivascular fluid exchange processes in 133 NT1 patients, 145 patients with other sleeping disorders, and 62 controls." (PMID 41981775, 2026).
Ventriculomegaly (8 papers, 2010 to 2025). An increase in size of the ventricular system of the brain. "This loss of AQP4 polarization also correlated well with ventricular dilatation (r = −0.586, p < 0.05)." (PMID 40046632, 2025). "We also find that Kidins220 deficient mice develop ventriculomegaly accompanied by water dyshomeostasis and loss of AQP4 in the brain ventricular ependymal layer and astrocytes." (PMID 34002021, 2021). "Given that AQP4 null mice show accelerated progression of ventriculomegaly relative to wild type controls, increases in cerebral AQP4 have been proposed to be neuroprotective." (PMID 36613677, 2022). "Very little is known about the molecules involved in the cellular processes that contribute to ventriculomegaly, although the water selective channel aquaporin-4 (AQP4) appears as a critical player." (PMID 34002021, 2021). "Together our data suggest that the KIDINS220-SNX27-retromer-AQP4 pathway is involved in human ventriculomegaly and open novel therapeutic perspectives." (PMID 34002021, 2021). "Nevertheless, in the aged AQP4−/− mice, which were protected from Hx-induced ventriculomegaly, the ventricular compliance was totally recovered after the ReNx period." (PMID 34575909, 2021). "In contrast, in the aged AQP4−/− mice, which did not develop ventriculomegaly in Hx, both parameters returned to normoxic control values in ReNx." (PMID 34575909, 2021). "In the AQP4−/− mice, both young and aged, the hypoxic treatment did not produce ventriculomegaly or alterations in the IVP values." (PMID 34575909, 2021).
autoimmune thyroiditis (7 papers, 2021 to 2025). "The observed link between AQP4-IgG-negative status and thyroid autoimmunity suggests that overlapping autoimmune risk alleles (e.g., CTLA-4 polymorphisms) or environmental triggers (e.g., iodine exposure) may influence self-reactivity." (PMID 40933045, 2025). "In contrast, none of the anti-AQP4-IgG− patients had SLE and only one patient had autoimmune thyroiditis." (PMID 33776892, 2021).
Brain atrophy (7 papers, 2022 to 2025). Partial or complete wasting (loss) of brain tissue that was once present. "The association of longitudinal brain atrophy with sGFAP suggests a possible link between astrocyte damage and subtle neurodegeneration in AQP4-IgG+NMOSD." (PMID 40693183, 2025). "Finally, brain atrophy was analyzed in a longitudinal fashion, increasing the validity of its association with sGFAP in AQP4-IgG+NMOSD." (PMID 40693183, 2025). "Therefore, further investigation is required regarding the underlying mechanisms of brain atrophy in patients with AQP4 + NMOSD." (PMID 37537208, 2023). "Thus, we hypothesized that subclinical dying back degeneration caused by long cord lesion contributed to the brain atrophy in patients with AQP4 + NMOSD." (PMID 37537208, 2023). "Therefore, not only dying back degeneration but also subclinical active lesions may cause brain atrophy in patients with AQP4 + NMOSD." (PMID 37537208, 2023). "We compared longitudinal brain atrophy in patients with AQP4 + NMOSD to longitudinal brain atrophy in patients with MS and showed that brain atrophy silently progressed in patients with AQP4 + NMOSD, even in clinically inactive patients." (PMID 37537208, 2023). "Additionally, those with LETM in AQP4+ NMOSD (AQP4+ LETM) exhibit reduced brain volume with an accelerated rate of brain atrophy, which indicate the impact of LETM on the brain structural changes." (PMID 40799281, 2025). "These subclinical microscopic active inflammatory lesions in the brain may result in higher longitudinal brain atrophy rates in patients with AQP4 + NMOSD." (PMID 37537208, 2023). "Moreover, these animals exhibited amplified cognitive impairments during memory tasks, along with intensified brain atrophy, indicating that the modulation of AQP4 function and, consequently, the glymphatic system can significantly influence the pathogenic propagation of tau throughout the brain." (PMID 38576025, 2024). "Suppressing disease activity may prevent brain atrophy in patients with AQP4 + NMOSD." (PMID 37537208, 2023). "The absence of an association between sGFAP and longitudinal brain atrophy in MOGAD as well as between sNfL and longitudinal brain atrophy in AQP4-IgG+NMOSD suggests a disease-specific process." (PMID 40693183, 2025). "Therefore, if silent progression by subclinical dying back degeneration occurs in patients with AQP4 + NMOSD, as we hypothesized, then biological disease-modifying drugs can prevent brain atrophy by decreasing the activity and lesion length in the spinal cord." (PMID 37537208, 2023). "Longitudinal brain atrophy, as assessed by PBVC, did not substantially differ between patients with AQP4-IgG+NMOSD and MOGAD." (PMID 40693183, 2025). "Reports on attack-related and chronic-progressive brain atrophy in AQP4-IgG-positive NMOSD exist, but data on the structured involved and the severity vary among studies; currently, monitoring of brain atrophy is not generally recommended outside of clinical studies." (PMID 37022481, 2023).